NGF (nerve growth factor)
Diseases named in the same sentence as NGF in open-access papers (continued):
Sharing a sentence is not in itself a finding about the gene and the disease.
gastric cancer (21 papers, 2017 to 2026). A primary or metastatic malignant neoplasm involving the stomach. "Although, it has been reported that NGF expression is associated with poor prognosis of gastric carcinomas, other reports found that the expression of NGF gene is higher in normal gastric tissue than in gastric cancer tissue." (PMID 28679437, 2017). "In gastric cancer, expanded enteric nerves and increased NGF expression are associated with the NGF/Trk signaling regulation of microtubule-associated doublecortin-like kinase 1 (DCLK1), also known as the tuft cell marker in normal tissue or the tumor stem cell marker in cancers." (PMID 37566075, 2023). "As shown in the stomach, stimulating the ACh–NGF axis may be sufficient to cause gastric cancer, where parasympathetic stimulation induces NGF expression within the stomach, promoting cholinergic axonogenesis and tumorigenesis." (PMID 36358664, 2022). "Similarly, higher expression of NGF mRNA was significantly associated with shorter OS of gastric cancer patients in search of OncoLnc database (Log-rank, p < 0.001)." (PMID 28679437, 2017). "In addition, the NGF-positivity was significantly associated with HO1-positivity in gastric carcinomas (p < 0.001)." (PMID 28679437, 2017). "NGF further promotes axonogenesis, increasing the density of vagus nerve in gastric cancer, forming a positive feedback loop between Ach‐NGF to promote gastric cancer initiation by activating YAP signaling." (PMID 41556039, 2026). "For example, SNRPA promotes gastric cancer cell growth by modulating the expression of nerve growth factor (NGF)." (PMID 41354732, 2025). "Cholinergic signaling has been established as a key factor mediating gastric cancer tumorigenesis via an NGF-promoted feedforward loop." (PMID 38723607, 2024). "In gastric cancer, the higher expression of SNRPA promotes gastric cancer cell development by activating NGF expression." (PMID 39845190, 2024). "Acetylcholine (ACh) also induced nerve growth factor (NGF) in a mouse gastric cancer model by stimulating its receptor‐muscarinic receptor‐3 (CHRM3), causing autocrine tumor advancements and paracrine increase of cholinergic hyper‐innervation." (PMID 38020711, 2023). "Chrm3 was also shown to induce NGF in gastric cancer cells, and the NGF then acts on TrkA receptors in the nearby nerves to facilitate tumor innervation, which is an example of how cholinergic signals promote tumor axonogenesis indirectly." (PMID 32477953, 2020). "In gastric cancer, cholinergic innervation is necessary for tumourigenesis and is driven by NGF release from cancer cells." (PMID 32001748, 2020). "A preclinical study showed that disturbance in ACh-NGF axis with anti-NGF antibody or downstream Trk inhibitors suppressed stomach cancer." (PMID 32733896, 2020). "Given that ACh-NGF-YAP axis promotes gastric tumorigenesis, inhibition of ACh, M3R, NGF is considered to be a potent therapeutic strategy against gastric cancer." (PMID 32733896, 2020). "In gastric cancer, NGF overexpression in the gastric epithelium expands enteric nerves that in turn promote the proliferation of epithelial stem cells, in part through acetylcholine/muscarinic receptor-3/Wnt signaling." (PMID 30988299, 2019). "In gastric cancer, NGF has been shown to activate cholinergic nerve-mediated signalling that stimulates the proliferation of stem cells." (PMID 29802376, 2018). "In our study, the expression patterns of NGF and HO1 in gastric cancer tissue were significantly associated with each other." (PMID 28679437, 2017). "Especially, the expression patterns of NGF and HO1 in gastric carcinomas were significantly associated with shorter OS and RFS." (PMID 28679437, 2017). "Three types of sub-groups of gastric carcinoma patients were grouped according to the largest area under the curve values for NGF and HO1 expression." (PMID 28679437, 2017).
gastric cancer (continued). "In this study, we demonstrate that substantial cases of gastric carcinomas express NGF and HO1, and their expression patterns are significantly associated with each other." (PMID 28679437, 2017). "Thereafter, we compared the prediction of death of gastric carcinoma patients with the individual or co-expression patterns of NGF and HO1 via receiver operating characteristic curve analysis." (PMID 28679437, 2017). "Gastric carcinoma patients with a NGF+/HO1+ expression pattern showed only a 33% five-year OS rate and a 19% ten-year OS rate." (PMID 28679437, 2017). "NGF inhibition attenuated nerve sprouting and tumor malignancy in gastric cancer." (PMID 41556039, 2026). "In gastric cancer, the combination of Ach and mAChRM3 can activate the overexpression of nerve growth factor (NGF) in the gastric epithelium, and NGF targets the TrkA receptor to increase synaptic growth, regulate mucosal innervation, and promote tumorigenesis." (PMID 41154659, 2025). "Moreover, NGF overexpression is sufficient per se to induce gastric cancer (GC) in rodent animal models." (PMID 31812953, 2019). "The mRNA levels of NGF and TrkA were lower in gastric cancer compared with normal gastric mucosa." (PMID 28679437, 2017). "Supportive of this hypothesis, we found that the expressions of both NGF and HO1 were significantly associated with shorter survival of gastric carcinoma patients." (PMID 28679437, 2017). "Although, the study for the NGF as a therapeutic target of gastric carcinoma is limited, our results suggest that NGF-related pathways are important in the progression of gastric carcinomas by presenting NGF expression as a prognostic marker of gastric carcinoma." (PMID 28679437, 2017). "Immunohistochemical expression scores for NGF (p = 0.003) and HO1 (p < 0.001) were significantly higher in gastric carcinomas (mean ± standard error: NGF; 3.1 ± 0.3, HO1; 4.5 ± 0.2) compared with normal gastric mucosa (mean ± standard error: NGF; 0.9 ± 0.4, HO1; 1.0 ± 0.3)." (PMID 28679437, 2017). "For example, NGF is overexpressed in gastric precancerous lesions, gastric cancer (GC), and CRC and maintains the proliferation of malignant cells." (PMID 40783715, 2025). "Similarly, a search of the Oncomine database (search condition: threshold p value; p < 0.001, threshold gene rank; top 10% gene, data type; mRNA) showed higher expression of HO1 mRNA in gastric carcinomas compared with normal gastric tissue although the expression of NGF mRNA was controversial." (PMID 28679437, 2017). "In spite of a study that has confirmed nerve growth factor (NGF) gene acts as a functional downstream effector of SNRPA and is essential for SNRPA modulated gastric cancer cells growth." (PMID 35392763, 2022). "To validate anti-NGF and anti-HO1 antibodies, we performed western blot with four human gastric cancer cell lines." (PMID 28679437, 2017). "Multiple oncogenic signaling pathways (gastrin-CREB, NGF-neurotrophin, PDGF, EGFR, ERK, ERBB4, FGFR1, RAS, VEGFR2 and RAF/MAP kinase) known to be active in aggressive gastric cancers were strikingly diminished in gastric cancers with low DOK6 expression." (PMID 29872697, 2017). "These mapped with high statistical significance to ten canonical signaling pathways, all of which were less active in low DOK6 gastric cancers: gastrin-CREB, NGF, PDGF, EGFR, ERKs, ERBB4, FGFR2, RAS, VEGFR2 and RAF/MAP kinase." (PMID 29872697, 2017). "First, we grouped gastric carcinomas into four-groups according to the expression types of NGF and HO1 (NGF−/HO1−, NGF+/HO1−, NGF−/HO1+, and NGF+/HO1+) and performed a Kaplan-Meier survival analysis." (PMID 28679437, 2017). "With this cut-off value, the expression of NGF and HO1 was positive in 40% (67 of 167 cases) and 51% (85 of 167 cases) of gastric carcinomas, respectively." (PMID 28679437, 2017). "The NGF+/HO1+ subgroup showed the shortest survival and the NGF−/HO1− subgroup of gastric carcinoma patients had the longest survival time." (PMID 28679437, 2017).
gastric cancer (continued). "Thereafter, we evaluated the expression of NGF and HO1 as a prognostic indicator for gastric carcinoma patients." (PMID 28679437, 2017). "Especially, the individualized HO1 expression and co-expression pattern of NGF and HO1 were independent indicators of poor prognosis of gastric carcinoma." (PMID 28679437, 2017). "We examined immunohistochemical expression of NGF and HO1 in 167 gastric carcinomas and compared with various prognostic clinicopathological factors." (PMID 28679437, 2017). "In conclusion, this study demonstrated that the expression of NGF and HO1 might be helpful for the estimation of prognosis of gastric carcinoma patients." (PMID 28679437, 2017). "HO1 expression (overall survival; p < 0.001, relapse-free survival; p = 0.002) and co-expression pattern of NGF and HO1 (overall survival; p = 0.002, relapse-free survival; p = 0.003) were independent poor prognostic indicators of gastric carcinoma patients by multivariate analysis." (PMID 28679437, 2017). "In addition, because there is a close relation between NGF and HO1 in malignant tumors, this study investigated the expression and correlation of NGF and HO1 in human gastric carcinoma tissues." (PMID 28679437, 2017). "However, despite extensive studies on the impact of NGF and HO1 in major human cancers, the studies on NGF and HO1 in gastric carcinoma are limited." (PMID 28679437, 2017). "Therefore, we investigated the expression and correlation of NGF and HO1 in human gastric carcinoma tissues." (PMID 28679437, 2017). "In addition, the expression patterns of NGF and HO1 were higher in gastric carcinomas compared with normal gastric mucosa." (PMID 28679437, 2017).
migraine (21 papers, 2005 to 2025). "Nine proteins—including CD6 and beta-NGF—were positively associated with migraine, while others like CCL19 showed inverse correlations." (PMID 40426647, 2025). "Among new variants associated with overall migraine is the common missense variant rs6330-A (p.Ala35Val) in NGF (OR = 1.035, P = 2.1 × 10−8)." (PMID 37884687, 2023). "We also acknowledge that our study faced several limitations; the case-control nature of the study prohibited us from drawing conclusions about causality and directionality between migraine and NGF, BDNF, VEGF, and PGE2 peripheral blood levels." (PMID 34991456, 2022). "NGF has been shown to play a critical role in the generation of pain and has been associated with migraine and pain severity in dysmenorrhoea." (PMID 28447608, 2017). "While we are unaware of any data linking GDNF with migraine, increased cerebrospinal fluid levels of NGF are associated with chronic headache." (PMID 15667652, 2005). "A variant near NGF is associated with migraine, a major headache disorder." (PMID 28447608, 2017). "The most studied within the migraine field are the neurotrophins NGF and BDNF; however, it should be noted that changes in other growth factors were also reported in migraine sufferers." (PMID 36982428, 2023). "Taking this into account, we aimed to investigate potential biomarkers associated with migraine in EM and CM patients with a special focus on PGE2, VEGF, NGF and BDNF." (PMID 34991456, 2022). "Nevertheless, the inconsistencies in the literature regarding the levels of NGF in patients with migraine warrants the need for further investigations to reach a more definite conclusion." (PMID 34991456, 2022). "Still, ASICs are activated by decreases in pH regulated in part by serotonin (5-HT) and nerve growth factor (NGF), changes in both of which are observed in migraine patients." (PMID 33799975, 2021). "One data point that supports a peripheral triggering event is that during a migraine attack, elevated levels of inflammatory mediators, such as nerve growth factor (NGF), bradykinin, prostaglandins, and eicosanoids, are observed." (PMID 30155469, 2018). "Possible relief from migraine symptoms may be achieved through the inhibition of the NGF/TRPV1/COX-2 pathway by Shaoyao Gancao Decoction." (PMID 38836002, 2024). "Examples of genetically anchored protein–disease connections included: TNFSF11 (RANKL) with osteoporosis and hypothyroidism, NGF (nerve growth factor) with migraine, TNFSF12 (TWEAK) with hypertension and fibroblast growth factor 5 (FGF5) with hypertension and cardiovascular diseases." (PMID 37563310, 2023). "TRPV1 is also sensitive to endocannabinoids, endovanilloids, nerve-growth factor (NGF), and prostaglandins (PGs), which may be relevant for migraine." (PMID 36614146, 2022). "One of the first TRP channels to be investigated was TRPV1, which is activated by capsaicin and also sensitive to endocannabinoids, endovanilloids, lipoxygenase metabolites, nerve-growth factor, and prostaglandins, among other factors many of which may be relevant for migraine." (PMID 30970581, 2019). "Our findings suggest that NGF, BDNF, PGE2, and VEGF may play a significant role in migraine pathogenesis and/or chronification, and therefore might bear potential value for novel targeted abortive and prophylactic migraine therapy." (PMID 34991456, 2022). "An analogous mechanism might also play a part in migraine, as satellite glia of the trigeminal ganglion express P2X7 and P2X3 receptors participate in craniofacial pain by interacting with NGF, substance P and CGRP." (PMID 24885962, 2014). "A fuller understanding of the impact of NGF, GDNF and BDNF on TG neurochemical properties has the potential to lead to novel therapeutic strategies concerning disease states involving neuropeptide secretion in the trigeminal system, such as migraine." (PMID 15667652, 2005).
migraine (continued). "For example, NGF blockade is most likely to attenuate inflammatory and peripheral sensitization mechanisms, whereas CGRP-targeted approaches may have greater relevance in migraine and other centrally mediated pain syndromes." (PMID 41012116, 2025).
ovarian carcinoma (21 papers, 2010 to 2026). A malignant neoplasm originating from the surface ovarian epithelium. "Especially worthy of attention is that we demonstrated for the first time that NGF is associated with β-catenin in human ovarian cancer migration in this article." (PMID 27835587, 2016). "In ovarian cancer cells, estrogen has also been demonstrated to promote the expression of angiogenic factors such as nerve growth factor (NGF) and vascular endothelial growth factor (VEGF) through the action of ERα." (PMID 39194700, 2024). "NGF (nerve growth factor) increases its expression during the progression of epithelial ovarian cancer, promoting cell proliferation and increasing vascularization through several oncogenic proteins such as c-MYC and VEGF." (PMID 35330327, 2022). "In particular, activation of the NGF/TrkA signaling pathway in human epithelial ovarian cancer cells can promote the metastasis of epithelial ovarian cancer by upregulating the expression of the vascular endothelial growth factor." (PMID 36032306, 2022). "Ovarian cancer cells express and secrete NGF, which directly stimulates endothelial cell proliferation by activating TrkA receptors to induce angiogenesis." (PMID 34307378, 2021). "The in vitro research on human ovarian cancer cell line A2780 showed that nerve growth factor (NGF) effectively stimulated cells for CRT expression." (PMID 33440842, 2021). "The results show that NGF increased the transcriptional activity of MYC in ovarian cancer cell lines (p < 0.05)." (PMID 33081077, 2020). "The main knowledge about miR-145 in ovarian cancer comes from miR-145-5p, so we decided to focus our study on miR-145-5p and its relationship with NGF/TRKA action in EOC cells." (PMID 33081171, 2020). "Summarizing, these results show that: (a) miR-23b levels are down-regulated in ovarian cancer, as has been reported; and (b) NGF reduces miR-23b levels in HOSE and A2780 cell lines." (PMID 28245631, 2017). "Nerve growth factor (NGF) and its high affinity receptor, Tyrosine kinase A receptor (TRKA), are overexpressed in ovarian cancer and they have been associated with increased proliferation, survival and angiogenesis." (PMID 28245631, 2017). "Next, we examined the phosphorylation level of TrkA in ovarian cancer cells under different culture conditions to investigate the biological relevance of NGF and β-catenin." (PMID 27835587, 2016). "Here, we determined the expression of NGFRs and endogenous NGF in the four different epithelial ovarian cancer cell lines by quantitative real-time PCR (qPCR) and western blot." (PMID 27835587, 2016). "We finally described the movement and migration behavior of ovarian cancer cells involving stimulation of NGF." (PMID 27835587, 2016). "All of these results confirmed that NGF/NGFRs-related inhibitors can both block the effects of endogenous and exogenous NGF on β-catenin expression in ovarian cancer cells." (PMID 27835587, 2016). "Especially, we created a novel in vitro cell growth model based on a microfluidic device to intuitively observe the effects of NGF/NGFRs on the motility behaviors of ovarian cancer cells." (PMID 27835587, 2016). "To study the possible mechanism of β-catenin down-regulation or activation status in NGF-stimulated ovarian cancer cells, we assessed the effect of NGF and the inhibitors of NGF/NGFRs upon phosphorylation of β-catenin." (PMID 27835587, 2016). "We chose 10 uM Ro 08-2750, 100 uM K252a, 5 nM LM11A-31 and 100 uM K252a+5 nM LM11A-31 which can completely block 100 ng/ml exogenous NGF-reduced expression of β-catenin to treat ovarian cancer cells that grown in serum-free medium containing 0.1% BSA." (PMID 27835587, 2016). "NGF acted as an autocrine or paracrine regulator of β-catenin which can decrease β-catenin expression and affect the activation status of β-catenin in ovarian cancer cells." (PMID 27835587, 2016). "Our results indicated that exogenous NGF can down-regulate the expression levels of β-catenin in ovarian cancer cells." (PMID 27835587, 2016).